CATSPERB (catsper channel auxiliary subunit beta)
Description:
Auxiliary component of the CatSper complex, a complex involved in sperm cell hyperactivation. Sperm cell hyperactivation is needed for sperm motility which is essential late in the preparation of sperm for fertilization.
Synonyms: C14orf161; FLJ14298; CatSper(beta)
Tractability: Antibody: its Gene Ontology location is reachable by antibodies, with high confidence; UniProt predicts a signal peptide or a membrane-spanning region.
Gene: Protein-coding gene on chromosome 14 (91,580,696 to 91,780,707, reverse strand). Ensembl gene ENSG00000133962.
Subcellular location: Cell projection, cilium, flagellum membrane
Subcellular location (Human Protein Atlas): Mid piece
Pathways (Reactome):
Reproduction: Sperm Motility And Taxes
Gene Ontology:
Biological process: flagellated sperm motility; sperm capacitation; spermatogenesis
Cellular component: CatSper complex; cilium; plasma membrane; sperm principal piece
Genetic constraint (gnomAD): Loss-of-function variants: 57 observed, 76.04 expected, observed/expected ratio (o/e) 0.75, 90% interval 0.61 to 0.94. The upper end of that interval is the gene's LOEUF score, 0.94, which puts it in group 3 of 6, group 1 being the genes least tolerant of losing a copy. Missense variants: 856 observed, 989.32 expected, observed/expected ratio (o/e) 0.87, 90% interval 0.82 to 0.92. Synonymous variants: 291 observed, 343.56 expected, observed/expected ratio (o/e) 0.85, 90% interval 0.77 to 0.93.
Homologues: Orthologues: chimpanzee CATSPERB (96% identical), macaque CATSPERB (89% identical), pig CATSPERB (74% identical), dog CATSPERB (72% identical), rabbit CATSPERB (69% identical), rat Catsperb (57% identical), mouse Catsperb (56% identical).
Diseases named in the same sentence as CATSPERB in open-access papers:
CATSPERB is named in the same sentence as 10 diseases in open-access papers, as found by Europe PMC text mining. Sharing a sentence is not in itself a finding about the gene and the disease. The quoted sentences say what the papers report.
gastric cancer (2 papers, 2021 to 2022). A primary or metastatic malignant neoplasm involving the stomach. "However, CatsperB could be used as a cancer-specific target to identify prostate, colon, esophagus, and stomach cancer, since no expression has been detected in their healthy counterpart tissues." (PMID 35330493, 2022).
asthenozoospermia (1 paper, 2021). "The relative abundance in transcripts of few TH2B associated genes- CREM, CDYL, PRKAG2, CATSPERB, TSGA10 and TSSK1B was studied in sperm of fertile and infertile men with asthenozoospermia-, oligozoospermia- or oligoasthenozoospermia." (PMID 33933143, 2021). "CATSPERB expression was apparently reduced in sperm of men with asthenozoospermia, but it was not statistically significant (p = 0.14) while in men with oligozoospermia it was unaltered." (PMID 33933143, 2021).
colorectal cancer (1 paper, 2022). A primary or metastatic malignant neoplasm that affects the colon or rectum. "CatsperB was found to be deleterious in colorectal cancer, namely serrated polyposis syndrome." (PMID 35330493, 2022).
lung carcinoma (1 paper, 2020). "In a recent study that recruited 28 highly-aggregated-extended-highrisk-familial-lung-cancer (HRFLC) families, highest cluster of genetic variants associated with lung cancer were identified within CATSPERB gene (14q32)." (PMID 33247676, 2020).
Sinus bradycardia (1 paper, 2021). Bradycardia related to a mean resting sinus rate of less than 50 beats per minute. "Therefore, all three genes DLG2, CATSPERB and RYR3 may not serve as susceptibility genes of sinus bradycardia induced by SGAs." (PMID 33914752, 2021).
cancer (3 papers, 2020 to 2022). A tumor composed of atypical neoplastic, often pleomorphic cells that invade other tissues. "“Genevisible” data analyses revealed CatsperB detectable in various human tissues including pancreas and colon and also in cancer of the prostate, pancreas, stomach, and esophagus." (PMID 35330493, 2022). "For some genes (CatsperB, CatsperD, Dysferlin, Fer1L5, Juno), a limited number of published literature referring to cancer is known." (PMID 35330493, 2022).
CATSPERB also shares sentences with these, for which no sentence is quoted: tumor (2 papers); colon cancer (1); infertile (1); stomach cancer (1).